MYB (MYB proto-oncogene, transcription factor)
Diseases named in the same sentence as MYB in open-access papers (continued):
Sharing a sentence is not in itself a finding about the gene and the disease.
tumor (continued). "While hallmark features of EMT were prominently observed in our analysis, an additional layer of evidence supporting the epithelial origin of the tumor lies in the marked upregulation of keratin expression within the non-MYB-expressing peripheral regions of the tumor architecture." (PMID 40950184, 2025). "Furthermore, the findings reveal that MYB overexpression counteracts the tumor-suppressive effects of miRNA-195-5p and activates the PI3K/AKT/mTOR signaling pathway, which promotes cancer progression." (PMID 41141380, 2025). "Furthermore, the MYB-ZFAT gene fusion has been identified in patients with blastic pDC neoplasm, a hematological malignancy derived from pDC precursors." (PMID 40213544, 2025). "To establish whether MYB is a functional downstream effector through which miRNA-195-5p exerts its tumor-suppressive effects, we performed a rescue experiment by overexpressing MYB in the context of miRNA-195-5p upregulation." (PMID 41141380, 2025). "The high expression of ERCC6L and MYB may be associated with the improvement of patients’ survival, suggesting that ERCC6L and MYB may play a potential protective role by inhibiting tumor progression or enhancing treatment sensitivity." (PMID 40672391, 2025). "It is noteworthy that the combination of cisplatin with the CEBPβ-regulated tumor suppressing long non-coding RNA (lncRNA) LOC102724169 showed synergistic effects in chronically stressed OC xenografts by suppression of MYB and phosphoinositide 3 kinase (PI3K)/protein kinase B (AKT) signaling." (PMID 38835346, 2024). "MYB-altered neoplasms are characterized by MYB overexpression, deriving from different mechanisms." (PMID 38544524, 2024). "Collectively, our results identified two previously unknown activated enhancers in BCP-ALL, which significantly modulated MYB expression and tumor cell proliferation, together with BCP-ALL growth and progression." (PMID 38926853, 2024). "In addition to overexpression, the presence of activated MYB-fusion proteins as tumor drivers was described in certain cancers." (PMID 38835346, 2024). "MYB proteins coincidentally exhibit tumor-suppressing properties, too." (PMID 38835346, 2024). "Importantly, immunofluorescence staining results showed that RSL3 treatment decreased MYB and Bcl-2 expression in the tumor tissues, which was further confirmed in western blot results." (PMID 38956026, 2024). "Metastatic lesions show increased NOTCH and MYB expression, promoting tumor migration." (PMID 39263605, 2024). "Furthermore, this tumor type is characterized by recurrent molecular alterations, especially rearrangements involving the MYB, MYBL1, and NFIB genes." (PMID 37476370, 2023). "In support of this hypothesis, the treatment of cultured MYB-positive ACC cells with phase 2 ATR kinase inhibitor VX-970 results in significant tumor growth inhibition and apoptosis." (PMID 37511133, 2023). "In the future, more precise and personalized immunotherapy may be achieved by elucidating the role of MYB in tumor development." (PMID 36994664, 2023). "Moreover, MYB expression is related to the tumor microenvironment and immune cell infiltration in different cancer types." (PMID 36994664, 2023). "Meanwhile, the correlation of MYB and immune checkpoint genes indicated that MYB may regulate tumor immunity in complex molecular pathways." (PMID 36994664, 2023). "We conclude that MYB may serve as a powerful biomarker for tumor screening, prognostic, individualized treatment strategy in a broad range of malignancies." (PMID 36994664, 2023). "TERT-promoter genes have been described in ACC tumours without MYB/MYBL1 fusions and without Notch mutations, possibly representing an alternative method of tumourigenesis." (PMID 37762061, 2023). "Since Black PCa patients tend to have worse outcome than White PCa even with a low-grade tumor, these data suggest that MYB could be a better predictor of PCa aggressiveness than Gleason’s grades." (PMID 38089573, 2023).
tumor (continued). "Moreover, lower expression level of MYB was detected in FAP (+) tumor-associated fibroblasts, suggesting a potential relationship between tumor microenvironment and MYB." (PMID 36994664, 2023). "Furthermore, the effect of MYB on tumor metastasis promotion was also investigated in an animal model, in vivo, through an injection of MYB overexpressing cells or control cells into the mouse tail vein." (PMID 37511133, 2023). "Overall, we found that MYB is related to tumor immunity in human cancers and may act as a novel predictor of immunotherapy." (PMID 36994664, 2023). "We next examined the association between the three model genes (CD36, BATF2 and MYB) and immunotherapy response using datasets composed of pre-treated tumor biopsies from responders and non-responders in the TIGER database." (PMID 37781029, 2023). "Copy‐number analysis revealed genomic events involving MYBL1 in four tumours and MYB in one tumour." (PMID 35836307, 2022). "Furthermore, it will also be very interesting to examine if combinations of MYB-inhibitory protein kinase inhibitors and other MYB-inhibitory agents exert synergistic effects MYB-dependent tumor cells." (PMID 35406726, 2022). "In addition, the immunohistochemical staining results showed that both Ki-67 and MYB were expressed at low levels in BC200-silenced tumor tissues." (PMID 35136029, 2022). "In support of our phenotypic observations made in tumor-derived organoids, the expression of MYB was also significantly down-regulated by the combined treatment of BBR and OPCs (FC = 0.40 vs control, P = 0.05 in patient #1; FC = 0.43 vs control, P = 0.03 in patient #2)." (PMID 35600365, 2022). "The tumor in Case 2 was positive for both MYB protein expression and rearrangement." (PMID 35590093, 2022). "MYB expression correlated positively with tumor grades and stages." (PMID 34145334, 2021). "The high expression of MYB mRNA might explain the high frequency of metastasis from tumours of the major salivary gland, especially those of the submandibular gland." (PMID 33449415, 2021). "In summary, hsa_circ_0015326 positively regulates MYB signaling and acts as a tumor-promoting factor; thus, its downregulation could be a potential therapeutic approach." (PMID 34876130, 2021). "Specifically, these mutations are located on five tumor suppressors (SDHA, RB1CC1, PTCH1, DMBT1, BCR) and eight proto-oncogenes (MERTK, CSF1R, MYB, ROS1, PCM1, FGFR2, MYH11, BRCC3) and have an allele frequency lower than 0.01 in the Genome Aggregation Database (GnomAD)." (PMID 33466296, 2021). "Meanwhile, MYB was upregulated in tumor tissues, but its higher expression showed better prognosis." (PMID 33926457, 2021). "Previous studies have indicated that MYB is a druggable transcription factor and suggested that strategies based on inhibition of MYB may open new therapeutic avenues for the treatment of neoplasms depending on deregulated MYB." (PMID 35008207, 2021). "Notably, many MYB-regulated miRNAs affect the development of cancer by targeting certain transcription factors and tumor suppressors." (PMID 34876130, 2021). "Coincidentally, miR-130a and miR-155 both promote tumor angiogenesis by targeting c-MYB." (PMID 34195097, 2021). "In addition, MYB was a canonical predicted target of miR-150, which impacted on proliferation of tumor cells in cooperation with miR-150." (PMID 33815136, 2021). "Because of the constant overexpression of SYCP2, MYB and underexpression of CAV1 in HNSCC, these may be considered potential biomarkers of neoplasms associated to HPV, in addition to p16 and CCND1." (PMID 34830760, 2021). "MYB at the protein level correlated positively with increasing tumor-grade and clinical stages." (PMID 34145334, 2021). "MYB oncoproteins; MYB, MYBL1, and MYBL2 plays important roles in the modulation of cell cycle, and dysregulation in these genes have been implicated with abberant behaviours of the tumour cells." (PMID 34921182, 2021).
tumor (continued). "Numerous studies have shown that MYB overexpression can promote the growth of tumor cells." (PMID 34876130, 2021). "In our patient's tumor, the fusion event resulted in an out-of-frame transcript encoding a truncated, constitutively active MYB protein that lacked the C-terminal cytoplasmic domain required to regulate its activity." (PMID 33733072, 2021). "To sum up, we speculate that MMP8, MMP11, TFDP3, F2, and CNTN1 can promote the progression of GAC while MYB could be a tumor suppressor in GAC." (PMID 32309437, 2020). "Likewise, these target genes are mainly related to the metabolic pathways, confirming the role of MYBBP1A in the regulation of the tumor cell metabolism through c-MYB and PGC-1α." (PMID 31968688, 2020). "In c-MYB + lines, the reduction in MYBBP1A levels causes an increase in the number of Cancer Stem Cells (CSCs) the capacity of tumor-formation and the expression of genes related to the regulation of the pluripotency of tumor stem cells and the epithelium–mesenchyme transition." (PMID 31968688, 2020). "The most common immunological tumor markers in ACC are MYB, CD43, and CD117." (PMID 31912868, 2020). "Our findings may also have implications for other types of neoplasms with activation of the MYB oncogene." (PMID 32001675, 2020). "Identification of a transcription program running in tumor cells with high MYB expression that prevents macrophage accumulation may open new venues towards better prognosis estimation and potentially towards TAMs targeting." (PMID 31406165, 2019). "Therefore, to explain very different c-Myb expression levels after Dox induction, we suggest, that MYB shRNA levels under the control of Tet-repressor–regulated H1 promoter were reduced in some tumor specimens because of specific silencing of H1 promoter." (PMID 31004084, 2019). "Like-wise, tumours that had lower MYB mRNA expression had corresponding lower MYB protein levels." (PMID 31301736, 2019). "Interestingly, the effect of MYBBP1A as a tumor suppressor is only observed in the presence of c-MYB." (PMID 30781655, 2019). "Here, we provide the first evidence that MYB gene TSS2 is activated in an ACC tumor." (PMID 31877778, 2019). "We propose that identified transcription program running in tumor cells with high MYB expression and preventing macrophage accumulation may open new venues towards TAMs targeting and BC therapy." (PMID 31406165, 2019). "Our work supports the theory that MYBBP1A acts as a tumor suppressor that interacts with c-MYB." (PMID 30781655, 2019). "Unique, tumor-specific interactions between a hijacked enhancer and the MYB gene promoter could provide a novel target for therapeutic intervention in ACC tumors." (PMID 31877778, 2019). "This may suggest that other MYB fusion transcripts possibly involving NFIB or other 3′ gene partners are present in these tumours." (PMID 31301736, 2019). "Teniposide and etoposide therefore act like double-edged swords that might be particularly effective to inhibit tumor cells with deregulated MYB." (PMID 30177851, 2018). "In the majority of tumor cells, the MYB break-apart probe showed a green/red signal ratio of 3 in case 3 and a red/green signal ratio of 3 in case 6, consistent with amplification of the 5′ and 3′ parts of MYB, respectively." (PMID 29731974, 2018). "Among them are cancer-related genes such as MYB and TGFBR1 as well as many immune-related genes such as CCR7 and FCRL3, whose prognostic association is likely to reflect the inflammatory process and the presence of lymphocytic cells in the tumour." (PMID 28059167, 2017). "Data suggest MYB is a tumor suppressor while it might be that MYBL1 is involved in tumor progression." (PMID 28966727, 2017). "However, MYB expression was increased in the majority of tumours (69%) and global gene expression analysis revealed that well‐established MYB target genes were up‐regulated in CYLD‐defective tumours." (PMID 26969893, 2016).
tumor (continued). "The discovery of the translocation between chromosome 6q and 9p and the identification of the resultant MYB-NFIB fusion in 2009, led to an important insight into the molecular pathogenesis of this malignancy and highlighted the tumor driving role of the MYB (myeloblastosis) proto-oncogene." (PMID 27533466, 2016). "None of the tumour samples expressed any of the MYB–NFIB fusion transcript variants tested for (data not shown)." (PMID 26969893, 2016). "Eleven of 16 tumour samples (69%) were MYB‐positive, ie they showed > 15% positive cells." (PMID 26969893, 2016). "Strategies based on detection of newly described genetic events (such as MYB activating super-enhancer translocations and alterations affecting another member of MYB transcription factor family-MYBL1) offer new hope for improved risk assessment, therapeutic intervention and tumor surveillance." (PMID 27533466, 2016). "Although MYB activation defines ACC tumorigenesis and MYB overexpression has been associated with a worse clinical outcome in patients with ACC, there may be heterogeneity of MYB staining within tumor samples." (PMID 25587024, 2014). "This confirms that c-MYB is an evolutionary conserved target of miR-150 and implies that miR-150/c-MYB interaction may also be important for oncogenesis and (or) tumor progression." (PMID 25232701, 2014). "Increased expression of MYB found in the tumor vs mets comparison (logFC 1.2) may also contribute to MMP1 down-regulation; Myb protein is known to up-regulate cathepsin D and MMP9 and down-regulate MMP1." (PMID 23405235, 2013). "ZEB1 and MYB may therefore act as biologic switches, translating molecular changes in the tumor microenvironment into alterations in cell state." (PMID 24283570, 2013). "Our studies have identified the combination of MYB inhibition with DIA treatment as a potentially effective combination therapy for ER positive breast cancer that not only suppresses proliferation but induces extensive tumor cell death." (PMID 20659323, 2010). "The ERCC6L and MYB genes could serve as prognostic markers by strengthening the link between lactylation modification and M2 polarization, offering a new target for anti-tumor strategies aimed at the “lactate metabolism-macrophage polarization” axis." (PMID 40672391, 2025). "Furthermore, the observed interactions between immune and tumour cells, including those involving transcription factors such as MYB and SOX6, emphasise the interplay between transcriptional regulation and cell communication in shaping the immune landscape of HB." (PMID 40099956, 2025). "Here we show that monotherapy with selective PRMT5 inhibitors induced a potent anti-tumor activity across several cellular and animal models of ACC, which was paralleled by downregulation of genes associated with ACC tumorigenesis, including MYB and MYC (the recognized drivers of ACC progression)." (PMID 39794830, 2025). "Genomic profiling revealed no actionable targets but NOTCH1 and KDM6A frameshift and CTCF splice site mutations (no MYB/L fusion) with a low tumor mutational burden (TMB), microsatellite stable (MSS) and negative programmed death ligand 1 (PD-L1) were observed." (PMID 39451738, 2024). "Furthermore, RSL3 inhibited tumor growth and decreased MYB and Bcl-2 expression in vivo." (PMID 38956026, 2024). "Notably, MYB transcription factors contribute significantly to chemotherapy resistance either as overexpressed oncogenes or as downregulated tumor suppressors, which mirrors the Janus-like character of MYB proteins in cancer progression and resistance formation." (PMID 38835346, 2024).
tumor (continued). "It is considered to activate KRAS transcription and may induce the expression of the proto-oncogene MYB, participating in facilitating aerobic glycolysis and other functions and is therefore involved in the tumor progression and metastasis of several cancer types." (PMID 35988113, 2022). "Future work will examine whether MYB-NFIB fusion is involved in promoting tumor metastasis." (PMID 35565392, 2022). "The variable expression of MYB in OC cases could also represent molecular heterogeneity resulting from genetic differences or epigenetic alterations in cell populations due to their exposure to the differing tumor microenvironment." (PMID 34145334, 2021). "Third, although luciferase studies proved the interaction between DANCR-miR-187-5p-MYB axis, whether the anti-tumour properties of LAs can be reversed requires more experiments to prove, such as using antagomir to inhibit miR-187-5p or overexpressing MYB in MCF-7 cells treated with LAs." (PMID 35096852, 2021). "Therefore, we examined NTT and MYB expression of eight mice tumor samples." (PMID 34616668, 2021). "However, the mechanisms of tumor resistance induced by MYB are still incompletely elucidated." (PMID 33850634, 2021). "Moreover, tumor cells are “addicted” to the higher level of MYB." (PMID 34876130, 2021). "Therefore, the ordinarily high MYB level may be due to the decreased expression of tumor suppressor miRNAs, such as miR-96, miR-34a, miR-15a/16, miR-193b-3p, miR-548c-3p and miR-155." (PMID 34876130, 2021). "NFIB is likely to have a tumour suppressive role independent of MYB(L) in this cancer as truncation mutations specific to NFIB have also been found as have translocations involving other partners (e.g. NFIB-MAN1A1, NFIB-PTPRD, NFIB-NKAIN2, NFIB-XRCC4 and NFIB-AIG1)." (PMID 27083054, 2016). "These MYB-low ACC tumor samples were tested at different times on different array platforms but still showed an identical ACC downstream gene expression patterns indicating both MYB-dependent and independent gene transcripts that were enriched for extracellular matrix products." (PMID 25587024, 2014). "We validated this observation by identifying 3 additional ACC tumor samples from the public microarray databases with low MYB levels suggesting that approximately 5-10% of ACC samples may have this alternate phenotype with negligible MYB levels." (PMID 25587024, 2014). "Suppressing the activity of e4 significantly reduced MYB expression, inhibited the Notch signaling, decreased the cell viability of CRC and gastric cancer cells and prevented the growth of tumor xenograft." (PMID 40234694, 2025). "Similar to MYB- or MYBL1-altered pLGGs, DLGG-MAPK tumors are expected to display consistent imaging characteristics throughout the tumor, potentially allowing radiologists to identify characteristic features macroscopically on MRI." (PMID 40668344, 2025). "In conclusion, this study identifies miRNA-195-5p as a key tumor suppressor in TNBC, functioning through the downregulation of MYB and consequential inhibition of the PI3K/AKT/mTOR signaling pathway." (PMID 41141380, 2025). "Retinoic acid agonists inhibited tumor growth in vivo in ACC patient‐derived xenograft models and decreased MYB binding at translocated enhancers, thereby potentially diminishing the MYB positive feedback loop driving ACC." (PMID 40249221, 2025). "We further present a visualization of gene expression dynamics for MYB, CD24, CDH11, and VIM along with the spatial pseudotime trajectory, highlighting the progressive transcriptional shifts asso1ciated with tumor progression and EMT56." (PMID 40950184, 2025). "Emerging evidence suggests that MYB is frequently overexpressed in TNBC, contributing to aggressive tumor characteristics and unfavorable patient prognoses." (PMID 41141380, 2025). "RNA sequencing identified the oncogenic fusion MYB/MYBL1::QKI, a known driver of this tumour subtype." (PMID 41033792, 2025).